INS (insulin)
Diseases named in the same sentence as INS in open-access papers (continued):
Sharing a sentence is not in itself a finding about the gene and the disease.
Insulin resistance (continued). "The reference tests used across the studies were HEC, the gold standard for measuring insulin sensitivity, HOMA-IR, which estimates insulin resistance from fasting glucose and insulin levels, and the Matsuda index, which assesses whole-body insulin sensitivity using oral glucose tolerance test data." (PMID 40560922, 2025). "Moreover, abnormalities in mitochondrial biogenesis and decreased oxidative activity contribute to lipid accumulation in insulin-dependent tissues, further exacerbating insulin resistance." (PMID 40806527, 2025). "Insulin resistance is characterized by a reduction in the normal physiological function of insulin." (PMID 41009733, 2025). "However, in contrast to previous findings, SIRT4 knockout mice initially exhibited enhanced insulin secretion, but this eventually led to glucose intolerance and insulin resistance." (PMID 40799515, 2025). "Insulin sensitizers, including thiazolidinediones and biguanides, reduce insulin resistance and may slow atherosclerosis progression." (PMID 40378162, 2025). "Moreover, these mice exhibited significant reduction of glucose tolerance as well as insulin resistance, accompanied by abnormal HbA1c and insulin levels." (PMID 40225857, 2025). "However, aberrant hepatic insulin action is a primary driver of insulin resistance, in which much higher circulating insulin levels are needed to control blood glucose levels." (PMID 39823117, 2025). "Evidence suggests that the extract may disrupt the endocrine system by inhibiting progesterone-mediated oocyte maturation and interfering with the insulin signaling pathway, potentially leading to mild inflammation, insulin resistance, and obesity." (PMID 41155632, 2025). "In the overall sample, a higher RER was associated with higher fasting glucose (1.7; 95% CI 0.66, 2.8; P = .002), higher fasting insulin, (1.9; 95% CI 1.3, 2.6; P ≤ .001), and consequently higher Homeostatic Model Assessment for Insulin Resistance (HOMA-IR) (0.52; 95% CI 0.34, 0.70; P ≤ .001)." (PMID 40182182, 2025). "Additionally, the magnitude of peripheral metabolic effects, like insulin secretion, glucagon suppression, and modulation of gut hormones, can also be influenced by a patient’s existing metabolic status and degree of insulin resistance." (PMID 41010364, 2025). "In type 2 diabetes mice, plasma insulin levels reflect insulin resistance and insulin secretion." (PMID 40136402, 2025). "However, it is well-accepted that hyperinsulinemia refers to an elevated blood insulin level, often seen in conditions like insulin resistance or metabolic syndrome." (PMID 40137469, 2025). "Insulin resistance(IR) is characterized as the phenomenon that at normal plasma insulin levels, target tissues fail to demonstrate the usual synergistic hypoglycemic effects, inhibit endogenous glucose production, suppress lipolysis, and promote glucose uptake." (PMID 41048425, 2025). "Since 1938 bypasses cell-surface receptors to activate the RISK pathway by directly binding PI3Kα, we hypothesized that, in contrast to insulin, 1938 would remain cardioprotective in the setting of insulin resistance." (PMID 40513100, 2025). "When paired together, significant improvements in glucose and insulin levels may represent early indicators of preventing insulin resistance." (PMID 41149620, 2025). "Second, insulin therapy may indirectly aggravate insulin resistance through a variety of factors, and further aggravate myocardial injury." (PMID 39957999, 2025). "Further supporting this, SHBG overexpression in transgenic mice protects against high-fat (with carbohydrate) diet (HFD)-induced obesity and insulin resistance, improving glucose tolerance, lowering insulin levels, and attenuating increases in leptin and resistin levels." (PMID 41586225, 2025).
Insulin resistance (continued). "However, in diabetic patients, insulin resistance interferes with the regulation of lipolysis by insulin, resulting in increased levels of free fatty acids in the blood and increased Aβ protein deposition." (PMID 39814004, 2025). "Despite similar fasting blood glucose, a greater area under the curve in glucose and insulin tolerance tests suggests that AO rats are glucose intolerant and express insulin resistance, which is in concordance with data obtained from animals with diet-induced metabolic syndrome." (PMID 40427746, 2025). "Nanotechnology may make it possible to create insulin-releasing implants for women with PCOS-related insulin resistance, which would enhance their metabolic health and reproductive results." (PMID 41370421, 2025). "CAG:471 and Firmicutes bacterium CAG:83 due to excessive sedentary time may impair insulin signalling and promote insulin resistance." (PMID 40413611, 2025). "In addition, fasting insulin (β= -0.003, p= 0.017) and homeostasis model assessment of insulin resistance (HOMAIR; β= 0.003, p= 0.025) values showed an inverse linear relationship with relative handgrip strength." (PMID 39756373, 2025). "Whereas females from both genotypes showed no detectable changes in fasting glucose, glucose tolerance and insulin levels, PmchΔVglut2 male mice exhibited a slight improvement in glucose handling (time point: 15 min), and a notable amelioration of insulin resistance when fed a HFD." (PMID 40770666, 2025). "This inflammatory state could profoundly impair insulin signalling and contribute to major complications, including insulin resistance, type 2 diabetes, and cardiovascular disease." (PMID 41226484, 2025). "The blood–brain barrier can limit insulin transport into the CNS during the circumstances of hyperinsulinemia or insulin resistance, which could reduce insulin’s neuroprotective effects despite systemic therapy." (PMID 41023469, 2025). "Furthermore, exercising promotes skeletal muscle glucose uptake, improves insulin sensitivity and insulin resistance, and elevates glucose transport." (PMID 40391012, 2025). "Pregnant women may benefit from probiotics in maintaining serum insulin levels and potentially warding off insulin resistance." (PMID 39980689, 2025). "Insulin resistance, which is linked to prediabetes and Type 2 diabetes, is a condition when cells do not respond to insulin well, leading to elevated blood sugar levels." (PMID 39823117, 2025). "However, the core pathological mechanisms primarily involve pancreatic β-cell dysfunction and insulin resistance (IR), driving therapeutic strategies focused on enhancing insulin secretion and improving insulin sensitivity." (PMID 40647154, 2025). "The pathogenesis of T2D likewise implicates inflammatory processes, where the low-grade systemic inflammation could produce insulin resistance in most insulin-sensitive tissues." (PMID 40362446, 2025). "Worsening insulin resistance in an inflammatory state, results in inflammatory factors interfering with insulin signaling pathways, and further reducing the sensitivity of cells to insulin." (PMID 40650120, 2025). "GLP-1RAs stimulate glucose-dependent insulin secretion and may alleviate hyperinsulinemia by improving insulin resistance." (PMID 41011232, 2025). "However, insulin resistance develops and is characterized by a surplus of insulin that cannot effectively perform its function." (PMID 40182806, 2025). "They work to impair insulin secretion and mechanisms related to insulin resistance." (PMID 39835172, 2025). "Pharmacological treatments such as oral contraceptives, antiandrogens, insulin sensitizers, and ovulation-inducing agents can help hormonal imbalances, irregular menstruation, reproductive challenges, and metabolic issues like insulin resistance and dyslipidemia." (PMID 40700266, 2025).
Insulin resistance (continued). "Additionally, inflammation can impact the endocrine system, such as disrupting insulin signaling, leading to insulin resistance and abnormal glucose metabolism, further increasing the risk of cardiovascular disease and other complications." (PMID 40313943, 2025). "Insulin resistance (IR) is a condition that affects the body’s ability to use insulin effectively." (PMID 40851089, 2025). "Also, in AD, insulin signaling becomes impaired, a condition referred to as brain insulin resistance." (PMID 41155642, 2025). "This sexual dimorphism in stress perception and estradiol fluctuations may underscore the enhanced insulin response and insulin resistance frequently observed in females relative to males." (PMID 40777199, 2025). "Insulin resistance could play a pathogenetic role in this process by forcing compensatory insulin secretion to maintain normoglycemia and thus promote antigen presentation and faster loss of β-cell functionality." (PMID 39998445, 2025). "Interestingly, this effect is similar to the effect of CP on insulin levels and insulin resistance in fructose-fed rats, in agreement with the literature that show a correlation between these parameters." (PMID 40227203, 2025). "PLP, by increasing the GSH/GSSG ratio, may protect against obesity and insulin resistance by reducing oxidative stress and enhancing insulin sensitivity." (PMID 40584440, 2025). "Furthermore, it mitigated insulin resistance by upregulating the expression of insulin‐sensitive factors, such as GLUT4 and IRS2, while concurrently downregulating insulin resistance factors, including PTP1B and SOCS3." (PMID 40994455, 2025). "However, three different dietary interventions that improved insulin sensitivity and/or decreased insulin resistance all increased mtDNA DAMPs." (PMID 41156500, 2025). "Insulin resistance refers to the decreased sensitivity of target organs to insulin." (PMID 39859663, 2025). "Insulin resistance (IR), defined as an impaired biological response to insulin stimulation in target tissues, leads to hyperglycemia and compensatory hyperinsulinemia due to increased insulin secretion from pancreatic beta cells." (PMID 41464869, 2025). "Additionally, insulin resistance can alter brain insulin signaling, synaptic plasticity, and overall lead to cognitive decline." (PMID 40566634, 2025). "Insulin resistance increases in puberty and manifests as higher circulating insulin." (PMID 40143821, 2025). "SW treatment (50 mg/kg, i.p.)reduced serum triglyceride, cholesterol, and low-density lipoprotein (LDL) levels in diabetic animals and significantly increased the insulin sensitivity index, thereby improving the dyslipidemic condition developed as a result of insulin resistance." (PMID 40801607, 2025). "Insulin should be started gradually to avoid hypoglycemia, but higher doses may be needed if insulin resistance is suspected." (PMID 40401174, 2025). "Upon binding to its bile acid-derived ligands, S1PR2 potentiates the PI3K/Akt insulin-signaling axis, thereby enhancing peripheral glucose uptake and improving insulin sensitivity, indicating that this receptor–ligand axis constitutes a promising therapeutic target for insulin resistance." (PMID 40807240, 2025). "These risk factors not only directly affect the structure and function of blood vessels and the myocardium but may also interfere with the insulin signaling pathway through complex mechanisms and aggravate insulin resistance." (PMID 40248150, 2025). "However, strong negative correlations between blood glucose levels and antioxidant and insulin levels suggest that hyperglycemia promotes oxidative stress and insulin resistance in both the periphery and the central nervous system." (PMID 40722940, 2025).
Insulin resistance (continued). "A review by X Meng demonstrated that TCM decoctions can reduce insulin resistance, increase the expression of insulin receptors, and stimulate insulin secretion from pancreatic β cells, thus effectively controlling blood glucose and mitigating target organ damage." (PMID 41189619, 2025). "Negatively influences insulin signaling, then enhances insulin resistance.Increases inflammation by stimulation of the production of pro-inflammatory cytokines.Contributes to various components of metabolic syndrome development, including hypertension, dyslipidemia, and abdominal obesity." (PMID 40370785, 2025). "Epiregulin levels showed a negative correlation with polycystic ovary syndrome status and were inversely associated with body mass index, waist circumference, Homeostatic Model Assessment Insulin Resistance, triglycerides, fasting insulin, fasting glucose, and testosterone." (PMID 40638469, 2025). "The results indicate that IRS1 or IRS2 may facilitate insulin action in the liver, thereby maintaining systemic glucose tolerance, particularly when β-cell function is able to offset insulin resistance." (PMID 40747301, 2025). "Insulin resistance is defined as the inability of a given amount of insulin to promote normal glucose uptake and utilization and can also be understood as reduced sensitivity and responsiveness to insulin action." (PMID 40549205, 2025). "Additionally, ATR reduced the basal metabolic rate and suppressed insulin-mediated Akt phosphorylation, contributing to insulin resistance." (PMID 41009549, 2025). "Interestingly, improvement of insulin resistance assessed by the oral glucose insulin sensitivity index (OGIS) is considered to be an indicator of improvement of MASLD." (PMID 40867852, 2025). "Additionally, IL-17 receptor deficiency impairs the phosphorylation and activation of key kinases in insulin signaling pathways, leading to compensatory hyperinsulinemia and exacerbation of insulin resistance." (PMID 40078991, 2025). "Anthropometric parameters, body composition, body fat percentage, surrogate markers of insulin sensitivity (Homeostasis model assessment of insulin resistance index—HOMA-IR and ISI Matsuda), and circulating levels of leptin and adiponectin were measured in all participants." (PMID 40075777, 2025). "In particular, ellagic acid decreased serum total testosterone (−0.6 ± 0.2 ng/mL; p < 0.05), fasting insulin (−3.5 ± 1.1 μIU/mL; p < 0.05), fasting blood sugar (−11.2 ± 3.6 mg/dL; p < 0.01), and Homeostatic Model Assessment of Insulin Resistance (HOMA-IR index) (−1.3 ± 0.4; p < 0.01)." (PMID 41268159, 2025). "When insulin secretion is insufficient to counteract insulin resistance, then T2DM results." (PMID 40881124, 2025). "Insulin resistance is a complicated pathophysiological disorder with impaired biologic response of target tissues to insulin stimulation, impaired ability to inhibit glucose production and stimulate peripheral glucose elimination, and often, hyperinsulinemia to maintain normoglycemia." (PMID 40943177, 2025). "The underlying mechanism may involve the ability of metformin in increasing the sensitivity of liver, muscle, fat, and other tissues to insulin, thereby lowering blood sugar levels and reducing insulin resistance." (PMID 39774829, 2025). "The HOMA model is a key method for assessing pancreatic islet function by referencing FBG and serum insulin levels to calculate HOMA-IS, HOMA-β, and HOMA-IR, thereby offering a systematic and comprehensive evaluation of insulin sensitivity, β-cell function, and insulin resistance." (PMID 39911803, 2025). "However, in this study, GGCP + Nissen was noted to be inferior to SG in terms of improving fasting blood glucose, glucose tolerance, insulin resistance, and increased secretion of insulin." (PMID 40442682, 2025).
Insulin resistance (continued). "Insulin resistance is characterized by diminished responsiveness of insulin receptors to insulin, leading to reduced glucose uptake, altered myocardial glucose metabolism, disrupted cardiac electrophysiology, and heightened susceptibility to ischemia-induced myocardial injury." (PMID 39811465, 2025). "As a result, it remains undetermined whether mice that showed spontaneous glycemic remission continued to exhibit insulin resistance or impaired insulin secretion." (PMID 41480368, 2025). "Additionally, significant gender-wise differences were observed in the clinical parameters, including homeostatic model assessment of insulin resistance, fasting insulin, and micronutrients (p < 0.05)." (PMID 40133369, 2025). "We hypothesized that habitual EE and RE training would result in differential effects on HSkMC insulin‐stimulated glucose metabolism and insulin signaling, and that prior training status would confer protection against fatty‐acid induced insulin resistance." (PMID 41029907, 2025). "Insulin resistance refers to the diminished sensitivity of target tissues to insulin stimulation." (PMID 40429815, 2025). "In the setting of insulin resistance, insulin signaling is impaired at the level of tyrosine phosphorylation of insulin receptor substrate (IRS)-1, which leads to downregulation of the phosphatidylinositol 3 kinase (PI3K)/AKT pathway and subsequent muscle wasting." (PMID 40237064, 2025). "This elevated expression may influence fetal metabolism by modulating insulin signaling pathways, potentially contributing to fetal hyperglycemia and thereby facilitating the development of fetal insulin resistance in GDM." (PMID 41373661, 2025). "Hence, the balance of IRS-1pTyr and IRS pSer/Thr protein determines the magnitude of insulin actions and plays a fundamental role in the progression of insulin resistance." (PMID 40362446, 2025). "Concurrently, calcium overload exacerbates insulin resistance by disrupting insulin signal transduction in peripheral tissues, while hyperinsulinemia further inhibits uric acid excretion through activation of the renal URAT1 transporter, creating a vicious cycle." (PMID 41301787, 2025). "Lifestyle interventions such as regular physical exercise have been shown to effectively suppress miR-221-3p expression, which can potentially mitigate the progression of obesity-induced insulin resistance and type 2 diabetes, ultimately improving insulin sensitivity." (PMID 41002956, 2025). "Impaired insulin action or insulin resistance initiates metabolic syndrome." (PMID 39859066, 2025). "Insulin resistance (IR), characterized by a reduced response to insulin in target tissues despite elevated insulin levels, plays a pivotal role in the development of several chronic conditions, including metabolic syndrome, atherosclerosis, and type 2 diabetes." (PMID 40551744, 2025). "Lanifibranor is an oral pan-PPAR agonist that seems to significantly enhance hepatic and peripheral insulin sensitivity, as demonstrated by reductions in fasting liver glucose production and hepatic insulin resistance (IR) index, as well as by improved insulin-stimulated muscle glucose disposal." (PMID 40004572, 2025). "Insufficient insulin action may stem from reduced insulin secretion (absolute or relative) or insulin resistance (decreased insulin sensitivity)." (PMID 40650275, 2025). "Insulin resistance can result in elevated insulin and insulin-like growth factor-1 levels, which excessively stimulate androgen secretion, disrupt normal follicular development and ovulation, and may ultimately lead to infertility." (PMID 39815248, 2025). "Indeed, insulin resistance, increased basal insulin levels, and beta cell dysfunction are all observed as a part of aging in C57BL/6 mice." (PMID 40298742, 2025).